PRF1 (perforin 1)
Diseases named in the same sentence as PRF1 in open-access papers (continued):
Sharing a sentence is not in itself a finding about the gene and the disease.
hematological malignancies (5 papers, 2011 to 2024). "Additional still undiscovered genetic defects, or possibly even environmental factors may possibly contribute along with the PRF1 variant to predispose carriers of this mutation to the development of familial hematological malignancies." (PMID 21936944, 2011). "In the cohort studied here, no PRF1 mutations predisposing their carriers to the development of hematological malignancies were identified." (PMID 21936944, 2011). "PRF1 germline mutations were therefore analyzed in a panel of families with aggregated hematological malignancies with or without solid tumors." (PMID 21936944, 2011). "This PRF1 variant does not predispose its carriers to hematological malignancies." (PMID 21936944, 2011). "Three of them harbor clinically relevant variants in genes with a probable role in the development of inherited forms of hematological malignancies (GATA1, MSH4 and PRF1)." (PMID 36765901, 2023).
immunodeficiency (5 papers, 2009 to 2025). Failure of the immune system to protect the body adequately from infection, due to the absence or insufficiency of some component process or substance. "Using this system, primary human immunodeficiency diseases can be reconstructed, such as perforin (Prf1)-deficient FHL, which causes a life-threatening EBV-related immunoproliferative syndrome in humans." (PMID 33732260, 2021). "The pysosequencing assay described in this report is highly suitable to quantify differences in the methylation of PRF1 in the various sub-populations of cells in blood from normal and subjects with chronic diseases of immune dysfunction." (PMID 19523225, 2009).
bacterial infection (2 papers, 2024). "The cytolytic granules have been shown to contain chemokines such as CCL3, CCL4 and CCL5 in addition to the classical mediators of cytotoxicity (GZMB, PRF1 and GNLY), in both viral and bacterial infections, indicating their role in cytolysis." (PMID 38501302, 2024). "Although uNK cells express granzymes and Prf1 even under normal circumstances, uNK cells do not exhibit killing of trophoblasts or fetal cells in the manner of peripheral blood NK cells, except under very specific circumstances, for example, in the event of viral or bacterial infection." (PMID 39656539, 2024).
adenocarcinoma (1 paper, 2019). A common cancer characterized by the presence of malignant glandular cells. "To evaluate intertumoral immune cytolytic T-cell activity across the colon (COAD) and rectum (READ) adenocarcinoma samples, we initially calculated the transcript levels of GZMA and PRF1." (PMID 31429779, 2019).
heart disease (1 paper, 2021). "Although there are currently no reports about PRF1 and TENM4 involved in heart disease, we noticed that they may be related to LMNA mutation-associated DCM in our research; therefore, they may be the potential biomarkers of DCM, which needs further verification." (PMID 33407844, 2021).
neoplastic disorders (1 paper, 2025). "Partial perforin deficiency, which is likely to be observed in heterozygous carriers of PRF1 alleles with impaired function, may be the cause of delayed FHL or other inflammatory or neoplastic disorders." (PMID 41374957, 2025).
PRF1 also shares sentences with these, for which no sentence is quoted: Hypofibrinogenemia (4 papers); cardiovascular disease (3); colitis (3); multiple sclerosis (3); myeloma (3); Chediak–Higashi Syndrom (2); depression (2); glioma (2); hematological cancers (2); Hepatosplenomegaly (2); hyperferritinemia (2); hypertriglyceridemia (2); lung squamous cell carcinoma (2); Lymphadenopathy (2); mitochondrial disease (2); non-Hodgkin lymphoma (2); Obesity (2); rheumatoid arthritis (2); sarcoma (2); Splenomegaly (2); abdominal aortic aneurysm (1); acquired aplastic anemia (1); acquired immunodeficiencies (1); adrenocortical carcinoma (1); AIDS (1); alopecia areata (1); aneurysm (1); ankylosing spondylitis (1); Arthritis (1); autoimmune lymphoproliferative syndrome (1).
A further 63 diseases each share a sentence with PRF1 in 1 paper.